CRP (C-reactive protein)
Diseases named in the same sentence as CRP in open-access papers (continued):
Sharing a sentence is not in itself a finding about the gene and the disease.
acute kidney injury (continued). "Laboratory parameters of elevated CRP (OR 1.652; 95% CI 1.28–2.14), AST, or ALT > 500 IU/L (OR 52.5; 95% CI 12.52–220.1) and acute kidney injury (AKI) (OR 103.5; 95% CI 13.26–807.78) during hospital stay increased the odds of dying." (PMID 32454916, 2020). "Laboratory tests revealed marked elevation of liver enzymes with coagulopathy and renal failure (AST, 22,291 IU/L; ALT, 7666 IU/L; PT-INR, 5.51; APTT, 73.6 s; Cre, 4.64 mg/dL; BUN, 83 mg/dL; CRP, 7.15 mg/dL; ferritin, 7668 ng/mL)." (PMID 30622725, 2019). "With the progression of cirrhosis and the development of HRS in renal failure, the interdependence of MDA and CRP positively correlated (C = 0.85; *p < .05)." (PMID 29658815, 2018). "The laboratory evaluation on admission showed a high CRP level without electrolyte imbalance or renal failure." (PMID 40909025, 2025). "Independent predictors of recurrence in multivariable analysis included acute kidney injury (AKI), elevated C-reactive protein (CRP) levels, higher serum bilirubin levels, a higher model for end-stage liver disease (MELD) score, proton-pump inhibitor (PPI) use, and lack of β-blocker use." (PMID 41353185, 2025). "Independent predictors were female sex (AOR 2.72, 95% CI 1.15–6.49, p = 0.02), consolidation in chest X-ray (AOR 3.38, 95% CI 1.13–10.1, p = 0.02), high C-reactive protein (CRP > 5 mg/dl, AOR 2.76, 95% CI 1.12–6.75, p = 0.03) and acute kidney injury (AOR 3.98, 95% CI 1.57–10.2, p < 0.01)." (PMID 38602629, 2024). "However, there was large heterogeneity in age, septic shock, acute kidney injury, metabolic acidosis, neoplasm, BUN, CRP, and albumin (I2 > 50%)." (PMID 39103964, 2024). "Because of the small database, the data regarding LVEF, renal failure, and CRP were unavailable; consequently, these indicators were not included in the present study and require further research in future investigations." (PMID 38751661, 2024). "Furthermore, among the analyzed markers, the NLR and MLR had shown a better predictive ability for survival in patients with cancer and acute kidney injury (AKI) in patients with severe acute pancreatitis compared to the classic inflammatory factors such as high-sensitivity CRP and TNF-α." (PMID 38156280, 2023). "This renal failure was determined by higher levels of TNF-α, CRP, IL-6, and IL-10." (PMID 36851766, 2023). "Patients with acute renal failure were more frequently referred to PRM units and had higher levels of troponin at the acute phase than patients discharged to their homes, but had lower CRP and troponin levels than patients referred to PRU." (PMID 35741459, 2022). "Besides temperature, age, body mass index and smoking habit, variables indicating pulmonary involvement (respiration rate, oxygen saturation, dyspnea), inflammation (CRP, LDH, lymphocyte counts), and acute kidney injury at diagnosis were identified." (PMID 34279815, 2022). "Clinical assessment of other blood markers of the inflammatory response (C-reactive protein), blood coagulation (D-dimer), and renal failure (creatinine) did not reveal any significant changes over time between the treatment groups." (PMID 35337143, 2022). "Initial investigations showed significantly raised inflammatory markers: C-reactive protein (CRP) of 287mg/L, total white blood cell count (WCC) of 32.1 × 109/L with a predominant neutrophilia of 28.2 × 109/L and acute kidney injury with serum creatinine 208μmol/L (CrCl 28ml/min)." (PMID 33743624, 2021). "Blood tests revealed leukopenia with a nuclear shift to the left, elevated C-reactive protein (CRP) and procalcitonin, severe respiratory failure (arterial blood gas pH 7.342, PaCO2 26.0 mmHg, PaO2 37.7 mmHg, HCO3− 13.7 mmol/l), renal failure and metabolic acidosis." (PMID 33243155, 2020). "In addition, they presented elevated LDH and acute phase reactants (CRP and ferritin), alterations in coagulation parameters (INR, fibrinogen, D-dimer), renal failure and alterations in transaminases." (PMID 33057443, 2020).
acute kidney injury (continued). "Inflammation is recognized as increase in concentration of positive acute phase proteins such as CRP (reaching as high as 5-10 mg/dL in renal failure) and decrease in negative acute phase proteins such as albumin and transferrin." (PMID 28487874, 2017). "This study evaluated the effect of foot immersion with or without neck cooling on systemic proteins associated with acute kidney injury (NGAL, KIM-1), intestinal enterocyte damage (IFABP), immune activation (sCD14) and systemic inflammation (IL-6, TNF-α, CRP) in older adults." (PMID 41178782, 2025). "The laboratory investigations in 50% of patients had deranged liver function test (LFT) and acute kidney injury (AKI), and 60% had raised inflammatory markers, namely, white blood cells (WBC) and C-reactive protein (CRP)." (PMID 38765387, 2024). "Further biochemical testing revealed elevated levels of C-reactive protein (CRP), procalcitonin (PCT), urea, and creatinine, indicating an inflammatory reaction and acute kidney injury (AKI)." (PMID 39224749, 2024). "Laboratory tests showed elevated erythrocyte sedimentation rate and elevated c-reactive protein that indicated inflammation and acutely elevated creatinine; he was hospitalized for presumed inguinal cellulitis that had not responded to oral antibiotics and acute kidney injury." (PMID 39946302, 2025). "Relevant laboratory data were pancytopenia, worsening acute renal failure (urea: 92 mg/dL, creatinine: 2.5 mg/dL), increased serum lambda and kappa chains, increased lactate dehydrogenase (493 U/L), and increased inflammatory parameters (CRP: 26.4 mg/dL) though with no leucocytosis." (PMID 38910633, 2024).
Anxiety (334 papers, 2008 to 2026). Intense feelings of nervousness, tension, or panic often arise in response to interpersonal stresses. "Anxiety has also been associated with higher levels of circulating inflammatory markers (e.g., IL-6, CRP), which can enhance pain sensitivity and reduce pain modulation capacity." (PMID 41303122, 2025). "Inother words, approximately 15% of the association between C-DII and anxiety wasexplained by CRP in our model." (PMID 40110388, 2025). "Among healthy young adults, anxiety symptoms were associated with larger innate immune responses to influenza vaccines, as measured by changes in cytokines, CRP, and expression of type 1 interferon and proinflammatory genes." (PMID 41176702, 2025). "The MR analysis suggests a potential causal role of CRP on any anxiety disorder (which covers a broad range of anxiety-related conditions including panic disorder, social phobia, agoraphobia, GAD)." (PMID 38699368, 2024). "Further examination of the CRP-anxiety association using MR provided some weak evidence of causality (β=0.12; p=0.054)." (PMID 38699368, 2024). "Findings from the Hispanic Community Health Study indicated an association between anxiety and depressive symptoms and CRP concentrations in diverse Latino populations." (PMID 39452916, 2024). "Our study identified significant correlations between younger age, underlying diseases, TBI classification, delirium, elevated CRP levels, lower self-efficacy, insomnia, and more severe anxiety symptoms." (PMID 39554848, 2024). "We aimed to study the association of anxiety and depressive symptoms as well as comorbid presentations, with circulating high sensitivity C-reactive protein (hsCRP) levels in a large Latino cohort of diverse heritages." (PMID 37594961, 2023). "The results of this analysis are meaningful in that they indicate that CRP is significantly associated not only with certain ACEs and adult chronic pain outcomes but also with anxiety symptoms." (PMID 37865679, 2023). "The association between anxiety and inflammation has been demonstrated in a recent study that showed elevated C-reactive protein (CRP) levels in suicidal patients with anxiety disorders." (PMID 37840785, 2023). "The objective of this study was to examine the relationships between reported ACEs, anxiety, and chronic pain and to assess the associations between ACEs, anxiety, and CRP levels, as well as the link between CRP and chronic pain." (PMID 37865679, 2023). "Growing evidence supports a positive association between anxiety and inflammatory cytokines, such as interleukin-6 and C-reactive protein, which are known to be elevated in individuals with frailty." (PMID 36908457, 2023). "We found that the mean of CRP levels at ages 9 and 15 mediated the associations between persistent high anxiety and psychotic outcomes at age 24 (i.e., PEs and PD)." (PMID 35151465, 2022). "Of note, when the continuous CRP measure was used, the association with loneliness was attenuated whilst a new association with anxiety was observed." (PMID 36198766, 2022). "The mean of C-reactive protein at ages 9 and 15 mediated the associations of persistent anxiety with PEs (bias-corrected estimate −0.001, p = .013) and PD (bias-corrected estimate 0.001, p = .003)." (PMID 35151465, 2022). "This study investigated associations of anxiety and stress-related disorders with inflammation, specifically C-reactive protein (CRP) levels." (PMID 35028602, 2022). "For example, depressive and anxiety symptoms have both been associated with increases in C-reactive protein (CRP), a marker of systemic inflammation." (PMID 35742759, 2022). "In CSF, sICAM-1 was associated with the presence of all three symptoms and CRP was associated with the presence of anxiety only." (PMID 35643540, 2022). "When using the continuous CRP variable, the CRP-loneliness association was attenuated, whilst a new association and interaction between CRP and anxiety was observed." (PMID 36198766, 2022).
Anxiety (continued). "•We explored the association of anxiety and stress-related disorders with C-reactive protein (CRP) using UK Biobank." (PMID 35028602, 2022). "The mediating role of the mean of CRP at ages 9 and 15 in the association between persistent anxiety and PD at age 24 also demonstrated a good model fit (χ2 = 2.80, p = .73, root mean square error of approximation 0, comparative fit index 1.00)." (PMID 35151465, 2022). "The mediating role that CRP exerted in the association between persistent high levels of anxiety across childhood and adolescence and both PEs and PD at 24 years is noteworthy." (PMID 35151465, 2022). "Previous studies investigating the links between gut microbiota and low-grade inflammation marker C-reactive protein found Ruminococcaceae, Akkermansia, and Lactobacillales to be associated with the risk of anxiety and depression." (PMID 36068280, 2022). "Overall, MR results showed that genetically predicted higher CRP levels were associated with lower risk of depressive and anxiety symptoms." (PMID 34135474, 2021). "In conclusion, we report evidence for associations of higher serum CRP concentrations with depressive and anxiety symptoms, which are stronger for depressive than for anxiety symptoms and, although less consistently, for women than for men." (PMID 34505025, 2021). "A previous clinical study showed that a social stress task, the Trier Social Stress Test, not only increased systemic levels of CRP and inflammatory cytokines, but also caused mood disturbance, including anger and anxiety." (PMID 34774052, 2021). "We assessed state and trait anxiety, showing that elevated CRP is more strongly associated with state anxiety in depressed individuals." (PMID 34729541, 2021). "Overall, CRP was associated with depressive and anxiety symptoms after adjusting for all potential confounding factors, but adjustment for BMI attenuated these associations to some extent." (PMID 34505025, 2021). "In sex-stratified MR analyses, higher genetically predicted CRP concentrations were associated with relatively lower risk for depressive symptoms in men, and with relatively lower risk for anxiety symptoms in women." (PMID 34505025, 2021). "More recently, higher concentrations of CRP were also found to be associated with increased prevalence of anxiety symptoms." (PMID 34729541, 2021). "In bi-variate probit regression analysis, we found evidence for a stronger association of CRP with depressive symptoms (OR=1·014; 95% CI, 1·011–1·017) than anxiety symptoms (OR=1·004; 95% CI, 1·002–1·007)." (PMID 34505025, 2021). "Greater TSPO levels in the brain were found to be associated with stress and anxiety and with higher circulating C-reactive protein levels in cannabis users." (PMID 34207524, 2021). "The relation between anxiety and inflammation has also been reported, as have relations among inflammatory markers, association between CRP and anxiety in population-based studies." (PMID 34588477, 2021). "The amounts of practice across interventions were correlated with reduced Salivary C-reactive protein, and the amounts of practice in the last 3 weeks were associated with an increase in hope and a trend-level decrease in the trait of anxiety." (PMID 28220101, 2017). "Sensitivity analyses for the association between CRP and fatigue, by excluding patients with a Hospital Anxiety Depression Scale anxiety score of 11 or more." (PMID 26599129, 2015). "Similarly, difficulties in regulating positive emotions were associated with increased CRP and IL-6 levels and various symptoms, such as chronic fatigue, anxiety, and somatic complaints." (PMID 41333345, 2025). "Anxiety and stress-related disorders, such as generalized anxiety disorder and panic disorder, have been associated with elevated inflammatory markers, including CRP." (PMID 40648989, 2025).
Anxiety (continued). "Additional variables related to aggressive, affiliative, and anxiety-like behaviors and their associations with (%ΔGlu) and cortisol, interleukin-6 (IL-6), and peripheral measures of systemic inflammation (C-reactive protein; CRP) were also examined." (PMID 40157907, 2025). "Some studies have also linked high CRP levels with anxiety, particularly in men, suggesting that hormonal differences may influence both inflammation and anxiety." (PMID 40277932, 2025). "When people with CRP levels of >10 mg/L were omitted, our linear regression analysis found that in addition to anxiety and insomnia, other symptoms positively associated with CRP included psychomotor retardation, agitation, and difficulties with work and other activities." (PMID 39359158, 2024). "There was weak evidence for a CRP-anxiety association using MR (β = 0.12; p = 0.054)." (PMID 39149475, 2024). "It was hypothesized that there would be a significant association between ACEs, anxiety, and chronic pain experiences, and that CRP may also relate to some or all of these variables." (PMID 37865679, 2023). "A second objective was to explore whether ACEs, anxiety, and chronic pain experiences in adults are also associated with the inflammatory biomarker CRP and examine its role in the ACE-anxiety-pain pathway." (PMID 37865679, 2023). "Although more research into the relationships is needed, the results of the present study are meaningful in that they highlight that elevated CRP is potentially associated not only with childhood trauma history and adult chronic pain outcomes but also with anxiety symptomology." (PMID 37865679, 2023). "Previous studies reported that an elevated CRP level is associated with both depression and anxiety, and that inflammatory processes might play a role in the pathogenesis of these disorders." (PMID 36525411, 2022). "Our findings provide new evidence suggesting that persistent high levels of anxiety are associated with psychosis, and this may be mediated by elevated CRP levels." (PMID 35151465, 2022). "Additionally, some studies have investigated associations between inflammatory markers and clinical anxiety in adolescents, where CRP was reported to be cross-sectionally associated with anxiety, yet not prospectively." (PMID 35360574, 2022). "Moreover, greater TSPO levels in these brain areas were associated with stress and anxiety and higher circulating C-reactive protein (CRP) levels in cannabis users." (PMID 35558424, 2022). "Finally, CRP levels mediated the prospective associations between persistent high levels of anxiety and psychosis at age 24 (i.e., PEs and PD)." (PMID 35151465, 2022). "Our results support the hypothesis that some anxiety and stress-related disorders may be associated with high levels of inflammatory markers, as measured by CRP." (PMID 35028602, 2022). "We hypothesized that persistent high levels of anxiety would be a risk factor for psychosis in young adulthood and that CRP levels would mediate these associations." (PMID 35151465, 2022). "Furthermore, it was not possible to longitudinally investigate the association between changes in anxiety/stress with changes in CRP levels." (PMID 35028602, 2022). "High levels of stress were associated with elevations of soluble CD14, lipopolysaccharide binding protein (LBP), and tumor necrosis factor–α, while anxiety was associated with elevated concentrations of C-reactive protein (CRP) in otherwise healthy pregnancies." (PMID 33301421, 2021). "MR analyses provided consistent results suggesting that genetically predicted higher IL-6 activity was associated with increased risk for depressive symptoms, while genetically-predicted higher CRP concentration was associated with decreased risks of depressive and anxiety symptoms." (PMID 34505025, 2021).